OSBPL7 (oxysterol binding protein like 7)
Synonyms: ORP7; MGC71150
Tractability: Antibody: UniProt places it where antibodies can reach, with high confidence; its Gene Ontology location is reachable by antibodies, with high confidence. PROTAC: ubiquitination databases record sites on it.
Gene: Protein-coding gene on chromosome 17 (47,807,367 to 47,821,803, reverse strand). Ensembl gene ENSG00000006025.
Subcellular location: Cytoplasm, cytosol; Endoplasmic reticulum membrane; Cell membrane
Subcellular location (Human Protein Atlas): Cytosol; Nucleoplasm; Plasma membrane
Pathways (Reactome):
Metabolism: Synthesis of bile acids and bile salts
Gene Ontology:
Molecular function: cholesterol binding; protein binding; sterol transfer activity; lipid binding
Biological process: cellular response to cholesterol; positive regulation of proteasomal protein catabolic process; bile acid biosynthetic process; regulation of autophagy; sterol transport
Cellular component: autophagosome; cytosol; perinuclear endoplasmic reticulum; plasma membrane; nuclear membrane; endoplasmic reticulum membrane
Genetic constraint (gnomAD): Loss-of-function variants: 66 observed, 114.74 expected, observed/expected ratio (o/e) 0.58, 90% interval 0.47 to 0.71. The upper end of that interval is the gene's LOEUF score, 0.71, which puts it in group 2 of 6, group 1 being the genes least tolerant of losing a copy. Missense variants: 890 observed, 1,124.2 expected, observed/expected ratio (o/e) 0.79, 90% interval 0.75 to 0.84. Synonymous variants: 436 observed, 442.07 expected, observed/expected ratio (o/e) 0.99, 90% interval 0.91 to 1.07.
Homologues: Orthologues: chimpanzee OSBPL7 (99% identical), macaque OSBPL7 (99% identical), pig OSBPL7 (94% identical), dog OSBPL7 (94% identical), rabbit OSBPL7 (94% identical), mouse Osbpl7 (92% identical), rat Osbpl7 (92% identical), guinea pig OSBPL7 (86% identical), zebrafish osbpl7 (45% identical), Drosophila melanogaster CG3860 (19% identical), Caenorhabditis elegans obr-2 (16% identical). Paralogues in human: OSBPL6 (52% identical), OSBPL3 (51% identical), OSBP (26% identical), OSBPL1A (26% identical), OSBP2 (25% identical), OSBPL2 (19% identical), OSBPL10 (18% identical), OSBPL5 (18% identical), OSBPL8 (18% identical), OSBPL11 (17% identical), OSBPL9 (16% identical).
Diseases named in the same sentence as OSBPL7 in open-access papers:
OSBPL7 is named in the same sentence as 11 diseases in open-access papers, as found by Europe PMC text mining. Sharing a sentence is not in itself a finding about the gene and the disease. The quoted sentences say what the papers report.
Hypercholesterolemia (2 papers, 2023 to 2024). An increased concentration of cholesterol in the blood. "Internal validation of the selected 45 variants in 677 Malay participants with hypercholesterolemia showed that a novel variant in OSBPL7 (c.651_652del) increases hypercholesterolemia risk by 17 times." (PMID 36980993, 2023). "Participants with the novel OSBPL7 (oxysterol-binding protein-like 7) c.651_652del variant had 17 times higher odds for hypercholesterolemia." (PMID 36980993, 2023). "We identified a novel OSBPL7 (c.651_652del) variant that increased the risk for hypercholesterolemia by 17 times." (PMID 36980993, 2023). "The combination of age, tobacco use, fasting blood glucose level, and family history of hyperlipidemia with OSBPL7 c.651_652del increased the hypercholesterolemia risk from 11% to 20.3%." (PMID 36980993, 2023). "This OSBPL7 variant is the first to be associated with hypercholesterolemia, particularly in Malays." (PMID 36980993, 2023). "Furthermore, the combination of age, tobacco use, fasting blood glucose level, and family history of hyperlipidemia with the presence of OSBPL7 c.651_652del increased the hypercholesterolemia risk by 8.3%." (PMID 36980993, 2023).
kidney disease (1 paper, 2021). "In conclusion, we show that small molecule drugs targeting OSBPL7 reveal an alternative mechanism to upregulate ABCA1, and may represent a promising new therapeutic strategy for the treatment of renal diseases and other disorders of cellular cholesterol homeostasis." (PMID 34341345, 2021).
OSBPL7 also shares sentences with these, for which no sentence is quoted: breast carcinoma (1 paper); cancer (1); cholangiocarcinoma (1); Cognitive impairment (1); eczema (1); Hyperglycemia (1); hyperlipidemia (1); lung carcinoma (1); pancreatic cancer (1).